MBNL2 (muscleblind like splicing regulator 2)
Diseases named in the same sentence as MBNL2 in open-access papers (continued):
Sharing a sentence is not in itself a finding about the gene and the disease.
tumor (23 papers, 2007 to 2026). "In this report, we further explore the molecular mechanism underlying the tumor suppressive function of MBNL2 in a panel of human cancers." (PMID 34659561, 2021). "In this study, we further explored the molecular mechanism underlying the tumor suppressive function of MBNL2 in a panel of human cancer cells." (PMID 34659561, 2021). "Positive MBNL2 expression in the HCCs exhibited a significant association with small tumor size (≤3 cm, P = 0.0108) and low tumor stage (Stage I, P = 0.0026)." (PMID 27564110, 2016). "Hypermethylation of MBNL2 is associated with downregulation of MBNL2 in tumor tissues." (PMID 34659561, 2021). "Based on the inhibitory effect of NBT on tumor metastasis and MBNL2 upregulation, we hypothesized that the inhibition of tumor metastasis by NBT was associated with the upregulation of the MBNL2 expression." (PMID 31320607, 2019). "MBNL2 is an RNA-binding protein that regulates alternative splicing and plays a key role in stem cell differentiation, tissue regeneration, and tumor suppression." (PMID 40993208, 2025). "Mutations in U2AF1 contribute to cancer progression and have been reported in several different cancer types including CRC56, while MBNL2 was reported as tumour suppressor in hepatocarcinogenesis." (PMID 35552415, 2022). "Collectively, these results demonstrate that MBNL2 not only regulates DNA damage response, but also controls tumor cell fate after DNA damage." (PMID 33466733, 2021). "G1/S transition is prevented by p21 due to its function of the cyclin-dependent kinase inhibitor, hence, depletion of p21 can promote cell cycle progression and cell proliferation; we then explore the role of MBNL2 in tumor cell proliferation." (PMID 33466733, 2021). "Here, we explore the function of the RNA-binding protein muscleblind-like splicing regulator 2 (MBNL2) on tumor cell proliferation and DNA damage response." (PMID 33466733, 2021). "We show here the methylation status of MBNL2 promoter is significantly higher in tumor tissues comparing to normal tissues." (PMID 34659561, 2021). "To study the function of MBNL2 on tumorigenesis and tumor progression, we performed transcriptome and gene expression analysis in the HCT116 cells transfected with control or MBNL2 siRNA." (PMID 33466733, 2021). "Except the well-studied function in DM, recent reports suggested that MBNL2 also participates in tumorigenesis and tumor progression." (PMID 34659561, 2021). "MBNL2 would further alter tumor cell fate after DNA damage, MBNL2 knockdown inhibiting DNA damage repair and DNA damage-induced senescence, but promoting DNA damage-induced apoptosis." (PMID 33466733, 2021). "Since MBNL2 showed a regulatory effect on DNA damage response, we then investigated its impact on tumor cell fate upon DNA damage." (PMID 33466733, 2021). "Among normalized genes were Hnrnpa1 and Mbnl2 mRNA expression, whose expression was significantly increased in hearts during advanced tumor burden." (PMID 34669013, 2021). "Together, these results further confirm the tumor suppressive function of MBNL2 in some types of human cancer." (PMID 34659561, 2021). "For example, hypoxia specifically induces Muscleblind-Like Protein 2 (MBNL2), therefore enhancing tumor cell proliferation." (PMID 33796526, 2021). "Collectively, these findings suggest that MBNL2 plays a tumor suppressive function through miR-182-MBNL2-AKT-EMT signaling pathways." (PMID 34659561, 2021). "MBNL2 overexpression significantly enhanced the inhibitory effect of NBT treatment on tumor cell migration in MDA-MB-231 cells compared to controls transduced with the empty vector." (PMID 31320607, 2019). "Tumor tissues derived from LV-MBNL2 transduced cells after NBT treatment exhibited an increase in the MBNL2 protein compared with the control groups." (PMID 31320607, 2019).
tumor (continued). "Since NBT significantly inhibited tumor metastasis and increased the expression of MBNL2, we assumed that MBNL2 was partially responsible for the inhibitory effect of NBT on tumor metastasis." (PMID 31320607, 2019). "Analysis of TCGA database showed that the expression of MBNL2 in tumor tissues from BC and LC patients was significantly downregulated compared with that in normal tissues, indicating an inhibitory role for MBNL2 in tumor metastasis." (PMID 31320607, 2019). "To examine the in vivo effect of MBNL2 on tumor metastasis, we designed a metastasis model by tail vein injection of MBNL2-overexpressing BC cells." (PMID 31320607, 2019). "We showed the role of MBNL2 in tumor metastasis, which raises the possibility of assessing the clinical association between MBNL2 and metastasis." (PMID 31320607, 2019). "In the Boyden chamber assay, knockdown of MBNL2 markedly increased tumor cell migration and invasion." (PMID 27564110, 2016). "The tumor suppression effect of MBNL2 is likely due to the cooperation of multiple genes regulated by MBNL2." (PMID 27564110, 2016). "Although the splicing patterns of several genes are regulated by MBNL2, identifying the chief regulating events in the tumor suppression of HCC is difficult." (PMID 27564110, 2016). "For data presentation, HCC with more than 10% of tumor cells showing immunostaining for MBNL2 was regarded as positive." (PMID 27564110, 2016). "In conclusion, our study showed that overexpression of MBNL2 inhibits tumor cell growth and invasion, and hence a favorable prognosis for HCC patients." (PMID 27564110, 2016). "The overexpression of MBNL2 in Hep-J5 cells suppressed proliferation, tumorsphere formation, migration, and in vitro invasion, and also reduced in vivo tumor growth in NOD/SCID mice." (PMID 27564110, 2016). "The overexpression of MBNL2 correlated with smaller tumor size (≤ 3 cm, P = 0.0108) and low tumor stage (Stage I, P = 0.0026), indicating that MBNL2 expression was lost in the late stage of HCC development." (PMID 27564110, 2016). "MBNL2, typically tumor-suppressive, promotes cancer when depleted but, in some contexts or stages of cancer, contributes to cancer development; it plays a key role in cardiac fibrosis, especially in the aging heart, promoting fibroblast senescence and fibrosis." (PMID 39941055, 2025). "Overexpression of MBNL2 inhibits cell proliferation, migration in vitro, and tumor growth in vivo." (PMID 36428626, 2022). "MBNL2 plays a tumor suppressive function through miR-182-MNL2-AKT-EMT signaling pathway." (PMID 34659561, 2021). "Moreover, MBNL2 alters tumor cell fate upon DNA damage, depletion of MBNL2 inhibiting DNA damage repair and DNA damage-induced cellular senescence, but provoking DNA damage-induced apoptosis." (PMID 33466733, 2021). "Thus, we propose that MBNL2 plays tumor suppressive function by modulating miR-182-MBNL2-AKT-EMT signaling pathway." (PMID 34659561, 2021). "MBNL2 modulates multiple pathways involving tumorigenesis and tumor progression." (PMID 34659561, 2021). "Interestingly, despite overexpressed in these cancer types, both studies showed that MBNL2 suppresses tumor progression." (PMID 34805186, 2021). "A study reported that MBNL2 was a tumor suppressor in hepatocarcinogenesis." (PMID 32027093, 2020). "In summary, we have provided evidence that MBNL2 may act as a potential regulator of tumor metastasis and a mediator of the effects of NBT." (PMID 31320607, 2019). "The levels of MBNL2 in the lung tissue also increased in MBNL2-transduced mice, suggesting that overexpression of MBNL2 may have been responsible for the inhibition of lung metastasis in the mouse tumor model." (PMID 31320607, 2019). "In our study, MBNL2 overexpression (>10% of tumor cells) was detected in 51 of 143 (35.1%) HCCs." (PMID 27564110, 2016). "However, in some specimens, MBNL2 was expressed in the compressed liver parenchyma adjacent to the tumor nodule." (PMID 27564110, 2016).
tumor (continued). "The MBNL2 staining was both cytoplasmic and nuclear in the tumor cells." (PMID 27564110, 2016). "Except p21 and cyclin D1, several members of the PI3K/AKT pathway are significantly differentially expressed after MBNL2 depletion, hence, MBNL2 may regulate DNA damage response and tumor cell proliferation through other unknown mechanisms, which needs further investigation." (PMID 33466733, 2021). "Most strikingly, our analysis revealed a seven-gene drug-tolerant signature in all four drug-tolerant cell lines, irrespective of chemotherapeutic treatment, parental cell line and tumour subgroup—LTBP1, MAP1A, MBNL2, LGALS1, PNRC1, DAB2 and PLAAT3." (PMID 36831428, 2023). "Among the upregulated genes, MBNL2, SEPT4, REPS2, OTUD5, and TXNIP were shown to play a tumor-suppressive role in many tumors." (PMID 36428626, 2022). "On the other hand, the increased expression of other RBP-coding genes such as RBM24 and MBNL2 (muscleblind-like 2) in CMS4 tumors and in EpCAMlo cells is in sharp contradiction with their alleged tumor suppressing roles in colon and other cancers." (PMID 36346211, 2022). "The expression levels of some key tumor metastasis-related proteins including phospho-AKT, vimentin, cofilin, and MMP-2 decreased in MBNL2 overexpressed cells." (PMID 31320607, 2019). "The expression of MBNL2 in HCC showed a heterogeneous distribution ranging from diffuse positive (>50%) in 21 cases (14.7%), heterogeneous positive (11-50%) in 30 cases (21.0%), to positive in few tumor cells (≤10%) in 33 cases (23.1%)." (PMID 27564110, 2016). "In contrast, MBNL2 depletion with RNA interference in Huh7 cells increased in vitro migration and invasion, but did not enhance tumor growth." (PMID 27564110, 2016). "Transcriptional profiling classified the Ta tumours as luminal (high expression of luminal markers such as GATA3, PPARG, FOXA1 and XBP1 as well as differentiation markers such as UPK1A and KRT20) as well as non-aggressive (high expression of SKAP2, FABP4, MBNL2 and ID1)." (PMID 28916750, 2017).
cancer (16 papers, 2016 to 2026). A tumor composed of atypical neoplastic, often pleomorphic cells that invade other tissues. "The enrichment analysis of MBNL2 correlated genes indicates the potential function of MBNL2 on cancer progression." (PMID 34659561, 2021). "MBNL2 regulates cancer cell migration and invasion by modulating PI3K/AKT-mediated epithelial-mesenchymal transition." (PMID 34659561, 2021). "miR-182 directly targets the expression of MBNL2, exogenous MBNL2 can overcome the promotive effect of miR-182 on cancer cell metastasis." (PMID 34659561, 2021). "We were keen to understand the upstream signals responsible for the decreased levels of MBNL2 in human cancers." (PMID 34659561, 2021). "Invasion assay demonstrated that overexpression of MBNL2 was sufficient to rescue the promotive effect of miR-182 on cancer cell metastasis." (PMID 34659561, 2021). "Western blot indicated that the level of the MBNL2 protein in cancer cells was much lower than that in HUVEC normal cells." (PMID 31320607, 2019). "In this study, we found that NBT significantly inhibited cancer metastasis both in vitro and in vivo and identified MBNL2 as a mediator of NBT’s effect on cell metastasis." (PMID 31320607, 2019). "Since the expression of MBNL2 is low in cancers, we examined the relationship of the level of MBNL2 to metastasis in BC and LC." (PMID 31320607, 2019). "MBNL2 was first identified as a regulator of muscular dystrophy, while its function in cancer was rarely examined until a recent study." (PMID 31320607, 2019). "Thus, the combination of Mbnl1 and Mbnl2 DKO is likely more deleterious to cancer cell growth than the knockout of either gene alone, again highlighting the likely functional redundancy of these proteins." (PMID 40305509, 2025). "We analyzed MBNL2 promoter methylation levels in different cancer types." (PMID 34659561, 2021). "Since miR-182 directly targets the expression of MBNL2, the upregulation of miR-182 may contribute to the downregulation of MBNL2 in these cancer types." (PMID 34659561, 2021). "High levels of MBNL2 promoter methylation and miR-182 may contribute to decreased MBNL2 expression in cancer tissues." (PMID 34659561, 2021). "To study the function of MBNL2 in human cancers, we analyzed TCGA RNA-seq data sets." (PMID 34659561, 2021). "miR-182 promotes cancer cell migration and invasion by inhibiting the expression of MBNL2." (PMID 34659561, 2021). "When taken together, we hypothesized that both DNA methylation and miR-182 may contribute to MBNL2 downregulation in cancer." (PMID 34659561, 2021). "We overexpressed MBNL2 in cancer cells and performed transcriptome and gene expression analysis." (PMID 34659561, 2021). "Since MBNL2 regulates the splicing pattern of ES cells, it may also likely to regulate the splicing pattern of cancer cells to promote tumorigenesis." (PMID 27564110, 2016). "According to GO term analysis, genes correlated with MBNL2 were significantly enriched for biological processes associated with membrane trafficking, TGF-beta signaling, VEGFR and EGF/EGFR signaling, which are all related to cancer cell invasion and metastasis." (PMID 34659561, 2021). "Furthermore, inhibition of cancer cell migration by NBT was enhanced when MBNL2 was overexpressed, and silencing of MBNL2 could partially eliminates the inhibitory effect of NBT on metastasis." (PMID 31320607, 2019). "Therefore, upregulation of MBNL2 by NBT may exert anti-cancer metastasis activity by affecting multiple targets such as phospho-AKT and EMT transformation." (PMID 31320607, 2019). "Hence, MBNL2 may be another example of cancer cells using embryonic processes to facilitate their growth and development." (PMID 27564110, 2016). "Taken together, these data indicate that Mbnl1 and, to a lesser degree, Mbnl2, have direct roles in modulating MHC Class I-dependent killing of cancer cells by antigen-specific T cells." (PMID 40305509, 2025).
cancer (continued). "We identified relationships between RBPs and various cancer types, including alterations in CREBBP and MBNL2 in adenocarcinomas of the lung, liver, prostate, rectum, stomach, and colon." (PMID 39595158, 2024). "The human homologs of the top three RNA binding proteins identified in our screen, MBNL2, MBNL1 and RBFOX2, are differentially regulated in cancer transcriptionally and post-transcriptionally through alternative splicing." (PMID 38114498, 2023). "Of note, MBNL2 regulates cancer migration and invasion through PI3K/AKT-mediated EMT and its overexpression in breast and cancer cell lines inhibits their metastatic potential." (PMID 36346211, 2022). "MBNL2 protein was absent or weakly detected in cancer tissues, whereas adjacent normal tissues expressed higher levels of MBNL2." (PMID 34659561, 2021). "We selected six DplUSE-containing genes (KIF20A, EXT2, CLDN12, MBNL2, MED18, DKC1) from the 31 orthologous genes identified by the bioinformatic script that are common to human, mouse, and zebrafish and that have a relevant physiological function in malignant neoplasms." (PMID 41505098, 2026).
neuromuscular disease (2 papers, 2013 to 2025). "For example, Mbnl1 and Mbnl2 sequestration is known to contribute significantly to cellular dysfunction via RNA misprocessing in neuromuscular disease." (PMID 40305509, 2025).
myopathy (1 paper, 2024). A disease of the muscle in which the muscle fibers do not function properly. "Thus, even with combined MBNL1 loss and partial MBNL2 depletion, there was upregulation of MuSCs in response to myopathy but limited dystrophic changes." (PMID 38473933, 2024). "Given the myopathic changes in Mbnl1−/−/Mbnl2+/− mice, and the lack of significant myopathy or changes in Pax7 expression and MuSCs in the individual knockout lines, we decided to evaluate the Mbnl1−/−/Mbnl2+/− mice for these parameters." (PMID 38473933, 2024).
MBNL2 also shares sentences with these, for which no sentence is quoted: prostate carcinoma (3 papers); lung adenocarcinoma (2); adenocarcinoma (1); alcoholism (1); Arrhythmia (1); bladder carcinoma (1); Cirrhosis (1); colorectal cancer (1); depression (1); fibrosis (1); gastric cancer (1); glioblastoma (1); glioma (1); head-neck squamous cell carcinoma (1); hypersomnia (1); lung squamous cell carcinoma (1); non-small cell lung carcinoma (1); pancreatic cancer (1); Parkinson disease (1); psoriasis (1); subarachnoid haemorrhage (1); X-linked Emery-Dreifuss muscular dystrophy (1).